CD4 (CD4 molecule)
Diseases named in the same sentence as CD4 in open-access papers (continued):
Sharing a sentence is not in itself a finding about the gene and the disease.
colitis (continued). "A lack of spontaneous colitis in NOD2−/− mice was also associated with increased proportions of CD4+ regulatory cell populations bearing the latency associated peptide (LAP) within the lamina propria, when compared with wild-type mice." (PMID 36012618, 2022). "In line with this, histological analysis revealed that Ihh HET CD4+ T cells potently induced colitis in Rag2−/− recipient mice which was characterized by mononuclear and polymorpho-nuclear mucosal to submucosal infiltration of inflammatory cells, crypt hyperplasia, and epithelial injury." (PMID 35835905, 2022). "CD4+ TRM cells from mice with DSS-induced colitis were heterogeneous and functionally distinct." (PMID 35844584, 2022). "Notably, IL-17A expression was largely increased in all the three subsets of CD4+ T cells during DSS-induced colitis." (PMID 35844584, 2022). "Furthermore, a trend towards decreased IFNγ expression was observed in the mLNs of Il36r−/− T cell recipient mice (p = 0.1), indicating that CD4+ T cell IL-36R signalling promotes the differentiation of Th1 responses during colitis." (PMID 35177818, 2022). "Bacteroides has been found to induce CD4 + T cells by enhancing anti-inflammatory IL-10 and suppressing pro-inflammatory IL-17 production through secreting polysaccharide A which is not only able to prevent but also cure experimental colitis in animals." (PMID 35151255, 2022). "In particular, L. reuteri treatment reduced the number of CD11b+CD11c+ dendritic cells (DCs) (p < 0.05), a major source of pro-inflammatory cytokines during colitis, whereas the number of Foxp3+CD4+ T cells in MLNs was increased compared to the DSS-only group (p < 0.001)." (PMID 35320932, 2022). "It was shown that both B-cells and CD8a+ T-cells expressing Galphai-2 were required to prevent the onset of disease in the CD4+CD45RB+ T-cell transfer colitis model, but the precise mechanism behind this remains unclear." (PMID 35163775, 2022). "For example, in a colitis model induced by the transfer of CD4+CD45RBhigh cells into severe combined immunodeficient (SCID) mice, a subpopulation of colonic CD40+CD90+αSMA− MCs was shown to secrete higher amounts of IL-6, CCL2, and CCL5 in response to interferon-γ (IFN-γ) and CD40L." (PMID 35563571, 2022). "Cumulatively, these data suggested that the severe colitis phenotype seen in TAGAP deficiency is critically mediated by the gut microbiota, is transferable via FMT, and is associated with increased numbers of colitogenic CD4+ T cells." (PMID 36704549, 2022). "Interestingly, we observed a minor increase in the percentage of IL-4-producing CD4+ T cells in the colitis mouse model, which was also reduced slightly by PYY 3–36." (PMID 35443853, 2022). "We analyzed whether oral sensitization using hCA I ameliorates inflammatory levels in the CD4+CD25− T cell transfer model of colitis." (PMID 36289244, 2022). "Using this approach, we tested the capacity of MP cell subpopulations to induce colitis by individually transferring CD127hi Sca1lo, CD127hi Sca1hi, CD127lo Sca1hi, and CD127lo Sca1lo Foxp3− MP CD4+ T cell subsets from Foxp3-reporter mice to Rag2 KO recipients." (PMID 35707543, 2022). "Transfer of Tbx21–/– naïve CD4+ T cells into Rag2–/– mice gives rise to a higher proportion of IL‐17A‐producing CD4+ T cells and more severe colitis compared to mice receiving WT naïve CD4+ T cells, suggesting that T‐bet restrains pathology in IL‐17‐driven colitis." (PMID 35092032, 2022). "Furthermore, that study observed a greater proportion of activated CD4+CD69+ T cells in the mesenteric lymph nodes of Sirt2−/− mice in response to DSS-induced colitis, suggesting a role for Sirt2 in limiting CD4+ TEFF cell functions." (PMID 35296782, 2022). "CD4+ T cell–derived cytokines such as IL-17A and IFNγ are pro-inflammatory and have been shown to be pathogenic in murine models and in patients with IBD, whereas Treg cells protect mice from DSS-induced colitis." (PMID 35844584, 2022).
colitis (continued). "The decreased percentage of CD8+CD69+CD103+ cells might be a result of the infiltration of circulating CD8+ T cells, pointing to the important role of CD4+ TRM cells in the pathogenesis of DSS-induced colitis." (PMID 35844584, 2022). "Notably, the number of CD4+ T cells expressing IL-17A was significantly increased in mice with DSS-induced colitis, while numbers of CD4+ T cells expressing IFNγ remained unchanged." (PMID 35844584, 2022). "Like Tr1 cells, the CD25-LAG-3+ CD4+ T cells were anergic and capable of suppressing colitis." (PMID 36389662, 2022). "Furthermore, we observed that CD4+ T cells from the ceca of R23FR mice with colitis (Day 56) lysed colonic epithelial cell enteroids from wild-type (WT) mice with an efficiency similar to that observed using primary epithelial cells as targets." (PMID 35468944, 2022). "Besides, the percentage of CD4+ CD25+ Treg cells in the mesenteric lymph nodes of mice with DSS-induced colitis was lower than that in normal group, while the percentage of CD4+ CD25+ Treg cells increased by recombinant IGFBP5 treatment." (PMID 36389828, 2022). "However, in PBL, the frequencies of CD4+ cells were significantly decreased in DSS-induced colitis mice compared with normal mice treated with T. halophilus (18.72 ± 2.61% vs. 35.30 ± 6.84%, p < 0.05)." (PMID 35741032, 2022). "CD69+CD103− CD4+ TRM cells could play an important role in controlling DSS-induced colitis by producing IL-17A." (PMID 35844584, 2022). "In IBD patients and colitis mice, the population of CD4+ T cells is significantly decreased." (PMID 35794311, 2022). "We transferred naïve CD4+ T cells (CD4+CD45RBhighCD25−) from WT or Aim2−/− donor mice to Rag1−/− recipients, which lack mature T and B cells, and evaluated the abundance of Treg cells and colitis development after a follow-up period of 15 weeks." (PMID 35216346, 2022). "TIGIT expression was similar in CD4+ T cells from the spleen of colitis or control mice." (PMID 35844584, 2022). "In addition, those who developed colitis also had significantly higher levels of Th1 and proliferative CD4+ T cells on-treatment." (PMID 36173679, 2022). "However, TSC1 deficiency inhibits IFN-γ expression in CD8+ T cells after bacterial antigen-stimulation and enhances IFN-γ production by CD4+ T cells and Th1 differentiation in mice with induced colitis." (PMID 36186130, 2022). "Thus, the existence of functional cytotoxic CD4+ T cells in the mucosa and the contribution of these cells to colitis remain unresolved." (PMID 35468944, 2022). "Thus, further studies will be warranted to investigate the interaction between iNKT cells and Foxp3−CD25+CD4+ T cells using the T cell transfer colitis model." (PMID 36499642, 2022). "The role of TH1 and TH17 cells in inflammatory disease is reflected by the induction of colitis upon adoptive transfer of naïve CD4+ T cells into Rag2–/– mice, which is marked by a wasting phenotype, inflamed colon, splenomegaly, and a TH1/TH17 hybrid‐driven inflammatory response." (PMID 35092032, 2022). "Importantly, we show expansion of specific T cell subsets within inflamed regions of the colon, including tissue-resident memory CD8+ T cells and Th1 CD4+ T cells in patients who developed colitis." (PMID 36173679, 2022). "CD4+ T cells have been shown to play an important immunoregulatory role in the gut, and the homeostatic balance between inflammation-constraining and colitogenic T cell populations is thought to be a key determinant of colitis disease activity." (PMID 36704549, 2022). "Here, IL-17A and IFNγ production was strongly increased in CD4+ T cells from mice with colitis." (PMID 35844584, 2022). "TIGIT expression was increased in CD4+ T cells in the gut of mice with DSS-induced colitis." (PMID 35844584, 2022). "In addition, previous evidence showed that purified Tregs prevented naive CD4+ T cell transfer-induced colitis in SCID mice." (PMID 35126527, 2022).
colitis (continued). "After induction of experimental colitis, the relative expression levels of CD-4, CD-8 and TLR-4 were significantly downregulated with increasing concentrations of QT-NPs, unlike the colitic non-treated group, which exhibited higher expression levels of these genes." (PMID 35884960, 2022). "Antibiotics can induce colitis and affect key immune parameters, such as increasing the numbers of significant target cells (Th17+ CD4 T cells) for SIV infection in the colon, which could negatively influence infectious disease models." (PMID 35442982, 2022). "CD69+CD103− CD4+ TRM cells were the major source of interleukin-17A (IL-17A) production in the colon and TIGIT deficiency protected mice from induction of experimental colitis by reducing IL-17A–producing CD69+CD103− CD4+ TRM cells." (PMID 35844584, 2022). "The deficiency of CXCL13 can effectively alleviate the occurrence and the development of DSS-induced colitis by limiting CD4+CXCR5+ T cells migration from mesenteric lymph nodes to secondary lymphoid organs, and thereby inducing local regulatory B cells increase in colon." (PMID 36172372, 2022). "Having established that CDK9 inhibition effectively suppresses IFN-γ and TNF-α production in CD4+ T cells, we reasoned that systemic delivery of CDK9i could abrogate experimental colitis." (PMID 35660024, 2022). "However, in the inflammatory condition of colitis, the number of CD4+Foxp3+ Tregs was reduced in the colon of mice with colitis treated with rTsPmy compared to those mice with colitis that received PBS only." (PMID 34336843, 2021). "To test this hypothesis, we performed additional colitis experiments in which Rag2−/− recipients were transferred with naive Cd25Y129H CD4+ T cells alone or in combination with WT or Cd25Y129H Treg cells." (PMID 33408345, 2021). "In addition, fructo-oligosaccharide has been shown to exert intestinal anti-inflammatory effect in CD4+CD62L+T cell transfer model of colitis in mice." (PMID 35223407, 2021). "However, the colitis observed here in Dohh-ΔT and Dhps-ΔT mice is believed to be primarily CD4+ T cell-mediated, and in the Odc−/− T cell transfer model purified CD4+ T cells alone accelerated colitis." (PMID 34216540, 2021). "For instance, both intraepithelial CD28- CD8+ and lamina propria CD28- CD8+ equally prevented development of colitis in the CD4+ CD45RBhigh-induced colitis mouse model indicating that their location might be reflecting their demand not their function." (PMID 34707610, 2021). "Additionally, DTR-mediated ablation of transferred Hobit+ CD4+ T cells protected recipient mice from colitis induction." (PMID 34440651, 2021). "In this study, we found that treatment with rTsPmy significantly increased the expression of TIGIT within CD4+Foxp3+ T cells and the proportion of CTLA4+Foxp3+ Treg cells in CD4+ T cells in mice with colitis compared with mice with colitis that received PBS only." (PMID 34336843, 2021). "To test if failed suppression of aberrant T cell activity by Tregs contributed to the fatal inflammation in Dohh-ΔT and Dhps-ΔT mice, we transferred naive WT CD45.1+ CD4+ T cells into Rag1−/− recipients to initiate colitis, together with Tregs sorted from WT and Dohh-ΔT mice." (PMID 34216540, 2021). "Additionally, transfer of CD8aa+T cells can inhibit colitis, induced by the adoptive transfer of CD4 T cells into severe combined immunodeficient mice." (PMID 35663772, 2021). "CD4+ T lymphocytes could regulate inflammatory reactions and protect the colon tissue during colitis." (PMID 35010997, 2021). "One research showed that adoptive transfer of naive CD4+ T cells to Rag1−/− recipients will lead to development of colitis; however, adoptive transfer of naive Bcl6−/− CD4+ T cells into Rag1−/− recipient cannot induce Tfh cell differentiation and the development of colitis." (PMID 34471409, 2021).
colitis (continued). "Besides its role in the stabilization of lipid rafts, apical protein trafficking and cell adhesion, galectin-4 was shown to exacerbate intestinal inflammation by stimulating CD4+ T-cells to produce IL-6 in a murine colitis model." (PMID 33805597, 2021). "In addition, the LIP of transferred T cells in Rag1-mutant mice is enhanced in the absence of peripheral autoimmune regulator (AIRE) and induces colitis because of the decreased proliferation of Foxp3+CD4+ Treg cells." (PMID 33923792, 2021). "A low baseline proportion of peripheral blood CD4+ Tregs has been reported to be associated with anti-CTLA-4-related colitis, while eosinophils had already been found in biopsy specimens from patients with anti-CTLA-4-induced hepatitis, rash and colitis." (PMID 34790123, 2021). "In addition, TLR2 expression on APCs is necessary to induce IL-10 producing CD4+ T cells and protection against colitis and EAE." (PMID 34025663, 2021). "Moreover, we recently established a mouse model of reversible CD4+ T cell transfer colitis, which allowed us to study the role of CD4+ T cells in disease onset." (PMID 34440651, 2021). "Furthermore, TRIM27 expression was elevated in the colon tissues of Crohn’s patients and in CD4+T cells in the mesenteric lymph nodes of DSS-induced colitis mice." (PMID 34956195, 2021). "To evaluate whether the therapeutic effect of the drug involved changes in the frequency of inflammatory and suppressive subsets of CD4+ T-cells, we induced colitis by the administration of DSS in the drinking water in mice treated with GSK-J4 or vehicle." (PMID 33446666, 2021). "Our experiment showed that the CSF could increase the CD4+CD8+ DP T-cell rate in colitis mice, which may be due to the increased CD4+ T cells and contribute to the inflammatory regulation in DSS-attacked mice." (PMID 35010997, 2021). "In the following experiments, we asked whether immunization with these epitopes can induce enough of pTregs and Tan cells to suppress an onset of wasting disease in CD4+CD45RBhigh model of colitis." (PMID 33139845, 2021). "Interestingly, the exacerbated intestinal inflammatory response observed in Lgals1−/− mice was alleviated by adoptive transfer of wild type Foxp3+CD4+ regulatory T cells at induction of colitis." (PMID 34262567, 2021). "B. vulgatus stimulates CD4 cells and secretes specific antigens to induce colitis." (PMID 34368009, 2021). "Anti-IL-21 mAb treatment also ameliorated CD4+CD25− T cell adoptive transfer (AdTr) Colitis." (PMID 34471409, 2021). "To further confirm that in the absence of endogenous galectin-1 a functional defect in the Foxp3+CD4+Treg cells is involved in the severe response to DSS-colitis observed in Lgals1−/− mice, we adoptively transferred CD25highCD127low/− Foxp3+CD4+Treg cells (WT/TRegs) into colitic Lgals1−/− mice." (PMID 34262567, 2021). "Similarly, in an immunocompetent mouse model of colitis expressing the carcinoembryonic antigen (CEA) in the small intestine, CEA-specific CAR CD4+ T regs inhibited colitis triggered by CEA-specific CAR CD4+ effector T cells." (PMID 34707610, 2021). "Also, in patients suffering from colitis or cGN, treatment with IL-10 or Tr1 cell–enriched CD4+ T cell cocktail has strong potential to inhibit inflammatory responses." (PMID 33937944, 2021). "It is well possible that upon erosion of the epithelial barrier following DSS exposure or upon colitis induction via transfer of CD4+ naïve T cells, PTPN2-expressing macrophages are able to take up antigens and trigger subsequent anti-inflammatory immune reactions in PTPN2fl/flxCD11cCre mice." (PMID 34201918, 2021). "We subsequently examined the anti-inflammatory effects of NEt-3IB in an experimental colitis model induced by transferring CD4+CD45RBhigh T cells into C.B-17-scid/scid mice and treating with chow containing 0.015% NEt-3IB (approximately 30 mg/kg/day) or with regular chow as a control." (PMID 34475823, 2021).
colitis (continued). "CD4+ TEM≥21% patients were not predisposed to colitis, thyroiditis or superior clinical responses to therapy." (PMID 33664251, 2021). "First, in this model, CEA-specific CAR CD4+ effector T cells significantly destroyed the epithelial barrier on mice that express CEA in the small intestine leading to colitis; hence, effector cells were triggered by a specific antigen presented on the epithelial cells." (PMID 34707610, 2021). "Severe colitis could, however, be induced in nude mice by transfer of activated/Th1 CD4+CD45RBlow T cells, whereas intraepithelial lymphocytes may play an important role in suppressing the development of chronic colitis in this model." (PMID 34287711, 2021). "Colitis is then induced by the intravenous injection of syngeneic CD4+ CD45RBhigh T cells." (PMID 34707610, 2021). "For instance, in an adoptive transfer colitis model when Treg-depleted memory/effector CD4+CD45RBlo T cells were transferred into RAG-1-/- mice, IL-22 derived from these memory/effector T cells is pathogenic, whereas IL-22 is protective when CD4+CD45RBhi naïve T cells were transferred." (PMID 34992594, 2021). "Colitis was induced in SCID mice by transferring CD4+/CD25− T cells from WT mice." (PMID 32076420, 2020). "Since both T cell subsets are linked with the development of colitis, it is likely that the reduction of these subsets is one of the contributing factors preventing T cell-mediated pathology by NCOR1-deficient CD4+ T cells." (PMID 32318068, 2020). "In CD4+ Tconv, ectopic expression of FOXP3 using retroviral vectors or by HDR of a strong promoter upstream of the FOXP3 coding sequences allowed generation of Treg that suppressed CD4+ Tconv not only in vitro but also inhibited GvHD, colitis or dermatitis in animal models." (PMID 33717052, 2020). "Notably, our previous study shows that CD69 knockout (KO) mice only develop slight dextran sodium sulphate (DSS)-induced colitis, and that the CD69 expression on CD4 T cells plays important roles in the pathogenesis of DSS-induced colitis." (PMID 33584659, 2020). "CD4+ Tm (CD4+ CD45RBhigh) cells isolated from the lamina propria of mice with colitis were cultured in vitro for 8 weeks and transplanted into SCID mice to cause acute colitis, and CD4+CD44+CD62L− memory T cells were found to overaggregate in the lamina propria of the colon." (PMID 33597887, 2020). "The upregulation of Treg activities in DSS-induced colitis was further confirmed by analysis of CD4 and CD25 expression using immunofluorescence, and CD4+CD25+ cells were found to increase in the EVs groups, and the primed EVs group had more regulatory cells in the colon than the naïve EVs group." (PMID 32034203, 2020). "In addition, we employed an adoptive transfer model of colitis to study the impact of NCOR1 deletion during CD4+ T cell-mediated autoinflammation." (PMID 32318068, 2020). "To determine whether the colitis was mediated by a Th1 or Th2 or Th17 response, we measured the cytokine profile from colonic epithelial scrapping of CD4-Cre+/TgMettl14FL/FL conditional knockout mice compared with littermate control mice." (PMID 32634481, 2020). "Further supporting the role for NR4A1 in repressing effector functions of CD4+ T cells, the adoptive transfer of naïve Nr4a1−/− CD4+ T cells into RAG-deficient mice induced more severe colitis than wild-type CD4+ T cells, with an increase in IFN-γ and IL-17 producing T cells in the colon." (PMID 33597928, 2020). "Interestingly, ZFP36L2-expressing iTregs have reduced suppression property on the proliferation of naïve CD4+ T cells in vitro as well as the development of the T cell transfer model of colitis." (PMID 32655569, 2020). "Importantly, we discovered that the population of CD4+CD25+ Treg cells was significantly decreased in DSS-induced colitis but enhanced after treatment with mSjci." (PMID 33469451, 2020).